CTAGE3P (CTAGE family member 3, pseudogene)
Description:
Tumor-associated antigen.
Synonyms: CTAGE3; cTAGE-3
Gene: Processed pseudogene on chromosome 13 (51,908,218 to 51,910,621, reverse strand). Ensembl gene ENSG00000232872.